MZF1 (myeloid zinc finger 1)
Diseases named in the same sentence as MZF1 in open-access papers (continued):
Sharing a sentence is not in itself a finding about the gene and the disease.
Hyperglycemia (1 paper, 2022). An increased concentration of glucose in the blood. "In the current study, it was assumed that MZF1 associates with SETD8 to regulate WNT5A transcription, thus resulting in hyperglycemia-induced glomerular endothelial inflammation in DN." (PMID 35350980, 2022). "MZF1 links with SETD8 to regulate WNT5A expression in HGECs, thus elevating levels of hyperglycemia-mediated inflammatory factors in glomerular endothelium of DN patients and rats." (PMID 35350980, 2022).
invasive breast carcinoma (1 paper, 2018). A carcinoma that infiltrates the breast parenchyma. "Thus, MZF1 may contribute to the progression of mammary ductal epithelial cells to abnormal cells confined in the duct, and finally to invasive breast cancer." (PMID 29396433, 2018).
invasive ductal carcinoma (1 paper, 2018). "MZF1 expression was increased when comparing normal tissues to invasive ductal carcinoma (IDC; grades 1–2)." (PMID 29396433, 2018).
lung fibrosis (1 paper, 2021). "Furthermore, to understand the dynamics of MZF1 expression in the lung fibrosis tissue, the GSE85359 (Mouse) and GSE40839 (Human) datasets were downloaded from NCBI." (PMID 34768749, 2021).
myocardial infarction (1 paper, 2020). Gross necrosis of the myocardium, as a result of interruption of the blood supply to the area, as in coronary thrombosis. "MZF1 is a transcriptional regulator of several proteins; one of them is the SERPINA3 (serine proteinase inhibitor A3), protein that has been recently suggested as a potential predictive marker of clinical outcomes in myocardial infarction." (PMID 31947776, 2020).
neuropathic pain (1 paper, 2019). Chronic pain caused by damage to nerve fibers. "The behavioral results showed that prior administration of MZF1 siRNA significantly prevented the CCI-induced mechanical allodynia and thermal hyperalgesia, while post administration of MZF1 siRNA reversed the established neuropathic pain induced by CCI." (PMID 31582966, 2019).
pancreatic ductal adenocarcinoma (1 paper, 2023). An infiltrating adenocarcinoma that arises from the epithelial cells of the pancreas. "High expression levels of SCAND1, SCAND2 and MZF1 genes were significantly correlated with enhanced prognosis of patients suffering from pancreatic ductal adenocarcinoma (DAC)." (PMID 36982267, 2023).
Parkinson disease (1 paper, 2025). A progressive degenerative disorder of the central nervous system characterized by loss of dopamine producing neurons in the substantia nigra and the presence of Lewy bodies in the substantia nigra and locus coeruleus. "However, MZF1 showed negative regulation in pathways like the isoprenoid biosynthetic process, regulation of endoplasmic reticulum stress-induced intrinsic apoptotic signaling pathway, Parkinson’s disease, and protein export." (PMID 40655141, 2025).
postmenopausal osteoporosis (1 paper, 2025). Metabolic disorder associated with fractures of the femoral neck, vertebrae, and distal forearm. "The downregulation of myeloid zinc finger 1 (MZF1) expression, which activates the Nrf2/GPX4 pathway and inhibits rankl-induced ferroptosis in osteoclasts during early cell differentiation, may be a key mechanism underlying ovarian removal (OVX) mice models of postmenopausal osteoporosis." (PMID 41551515, 2025).
promyelocytic leukemia (1 paper, 2020). "This site was identified by showing that overexpressed full-length MZF1 has the ability to accumulate into promyelocytic leukemia nuclear bodies (PML-NBs), a function which requires SUMOylation, and which could be abolished when this area was deleted from MZF1." (PMID 31963147, 2020).
urothelial carcinoma (1 paper, 2025). A malignant neoplasm derived from the transitional epithelium of the urinary tract (urinary bladder, ureter, urethra, or renal pelvis). "Conversely, in the IMvigor210 urothelial carcinoma cohort, MZF1 expression was positively correlated with response to anti-PD-L1 treatment, with high MZF1 expression associated with improved survival and extended overall survival compared to lower expression levels." (PMID 40655141, 2025).
viral myocarditis (1 paper, 2025). Myocarditis that is caused by an infection with a viral agent. "In STAD, MZF1 was a negative regulator in glycerolipid metabolism, oxidative phosphorylation, and antigen receptor-mediated signaling pathways, but positively regulated pathways like Vibrio cholerae infection, viral myocarditis, and monoamine transport." (PMID 40655141, 2025).
tumor (59 papers, 2007 to 2025). "Against this backdrop, the MZF1 gene, the focus of this study, has been shown to play a pivotal role in various biological processes associated with tumor invasion, metastasis, proliferation, and drug resistance." (PMID 40655141, 2025). "In the majority of cancer types, MZF1 showed a significant positive correlation with tumor malignancy, indicating that higher MZF1 copy numbers are associated with increased tumor invasiveness, proliferative capacity, and metastatic potential." (PMID 40655141, 2025). "Both ELAC1 and MZF1 were associated with PFI among the luminal A tumor samples in site-specific analyses." (PMID 36936429, 2023). "In summary, we demonstrate that MZF1 is associated with poor outcome of NB, and exerts oncogenic roles in aerobic glycolysis and tumor progression." (PMID 32042322, 2020). "TFAP2A and MZF1 have both been implicated in the regulation of genes that control tumour invasiveness and metastases and the pathological process of EMT is known to underpin many cancer types with evidence supporting its role in metastatic cancer cells." (PMID 26697505, 2016). "Further genomic analysis revealed that mutations, CNVs, and changes in MZF1 expression levels could influence tumor behavior and patient prognosis." (PMID 40655141, 2025). "Moreover, 3D-clustered hotspot mutations were found in the SCAN domain of MZF1 in patient-derived tumor specimens." (PMID 36552758, 2022). "Notably, in BRCA, MZF1 expression was found to be associated with the modulation of immune cell functions, suggesting that MZF1 not only serves as a potential biomarker for tumor growth but also affects the tumor’s response to immunotherapy." (PMID 40655141, 2025). "These cells exhibited lower proliferative capacity during culture, indicating the critical role of MZF1 in tumor cell proliferation." (PMID 40655141, 2025). "Collectively, these findings underscore the pivotal role of MZF1 in tumor biology and immune modulation." (PMID 40655141, 2025). "Future studies should further explore the interactions between MZF1 and immune evasion mechanisms, as well as its impact within the tumor microenvironment." (PMID 40655141, 2025). "For instance, MZF1-mediated regulation of miR-328-3p acts as a tumor suppressor by modulating CD44 expression in the progression of STAD." (PMID 40655141, 2025). "MZF1 promotes various types of cancers by targeting key regulators of tumor progression, including c-Myc, AXL, IGF1R, and PKCα." (PMID 40961095, 2025). "The potential of MZF1 as a therapeutic target in cancer treatment warrants further investigation, particularly in cancers where it plays a pivotal role in tumor progression and immune regulation." (PMID 40655141, 2025). "By evaluating the stromal index, immune index, and ESTIMATE scores across various tumor types, found that MZF1 expression was generally negatively correlated with the TME in most cancer types." (PMID 40655141, 2025). "The link between immune cell infiltration and MZF1 expression was intensively investigated to determine the interrelationship between MZF1 and tumour immunity." (PMID 40655141, 2025). "Utilizing the TISCH network tool, the expression levels of MZF1 were examined across 32 distinct cell types, encompassing immune cells, stromal cells, tumor cells, and functional cells." (PMID 40655141, 2025). "Among them, MZF1, OGT, LHX4, and MED12 have been implicated in tumor stemness, drug resistance, and immune escape mechanisms." (PMID 40963600, 2025). "Studies have found that MZF1 can promote the proliferation of tumor cells in CRC and inhibit cancer progression through apoptosis." (PMID 38730335, 2024). "Further IHC analysis of the xenograft tumor sections showed that MZF1 expression was higher after EGFR-TKIs+5-Aza treatment compared with EGFR-TKIs alone." (PMID 36778111, 2023). "Intriguingly, the myeloid zinc finger 1 (MZF1) possesses reversely dual roles in GC by promoting tumor proliferation or impeding cancer progression via apoptosis." (PMID 37174714, 2023).
tumor (continued). "MZF1 influences the tumor-derived MSC-to-myCAF transformation induced by OPN-mediated TGF-β1 production in MSCs, which then adopt a myCAF phenotype." (PMID 38124183, 2023). "These suggest that MZF1 alone is oncogenic, whereas repressing complexes of SCAND1 and MZF1 is tumor suppressor, depending on their gene expression in cancer cases." (PMID 36982267, 2023). "Reports have shown that tumor-derived OPN induces MSC transformation into CAFs via MZF1-mediated TGF-β expression to promote more aggressive local tumor growth and metastasis in breast cancer." (PMID 37065872, 2023). "Our data indicate that elevated expression of SCAND1 and MZF1 can reverse the hybrid EMT status of tumor cells to a more epithelial status, although vimentin and nuclear β-catenin remained, suggesting that the cells were not fully epithelial." (PMID 36552758, 2022). "Both SCAND1 and MZF1 overexpression significantly inhibited tumor cell proliferation, while SCAND1 overexpression more significantly inhibited it." (PMID 36552758, 2022). "In this study, we found that YY1 promoted the expression of MZF1 in NB cells, resulting in facilitated glycolytic gene expression and tumor progression." (PMID 32042322, 2020). "FTO induces tumor progression by targeting MZF1, reducing the m6A in MZF1 transcript, increasing the stability and thus increased expression of MZF1 mRNA." (PMID 32194861, 2020). "Using an invasion assay, we found that downregulation of Axl expression by silencing of E6 or MZF1 in HE6F cells highly suppressed tumour cell invasion." (PMID 28720772, 2017). "Recent evidence shows that MZF1 exerts oncogenic or tumor suppressive functions in different cell contexts." (PMID 27259238, 2016). "Knockout of MZF1 increases the proliferative potentials of hemopoietic progenitors and results in lethal neoplasia in mice." (PMID 27259238, 2016). "We next investigated the efficacy of miR-337-3p against MZF1-facilitated tumor growth and metastasis in vivo." (PMID 27259238, 2016). "In these cancers, MZF1 expression may influence the immune microenvironment and tumor immune evasion mechanisms." (PMID 40655141, 2025). "MZF1 also functions as a tumor suppressor in the hematopoietic compartment." (PMID 40655141, 2025). "The differential roles of MZF1 across various cancers may be attributed to the unique biological characteristics of these malignancies, their microenvironments, and the varying functions of MZF1 in different tumor types." (PMID 40655141, 2025). "Notably, MZF1 expression was markedly elevated in the majority of tumor types, particularly in CHOL, LIHC, BLCA, COAD, KIRC, PRAD, and PEAD." (PMID 40655141, 2025). "Specifically, hypermethylation may suppress MZF1 expression, thereby reducing tumor malignancy and improving patient survival outcomes." (PMID 40655141, 2025). "In the tumor microenvironment, MZF1 is mainly found in CD4 Tconv cells and monocytes/macrophages." (PMID 40655141, 2025). "In subsequent analyses, MZF1 was found to exhibit the most prevalent genetic alterations in UCS, suggesting that MZF1 may play a pivotal role in the initiation and progression of this particular tumor type." (PMID 40655141, 2025). "Future research may delve deeper into the relationship between MZF1 methylation, copy number variations, and their interactions with the tumor microenvironment and immune evasion mechanisms." (PMID 40655141, 2025). "Thus, future research should delve deeper into the specific mechanisms by which MZF1 exerts its effects within the tumor immune microenvironment, and further explore its potential to enhance the outcomes of cancer immunotherapy." (PMID 40655141, 2025). "In certain tumor types, such as UCS, genomic alterations in MZF1 are more pronounced and may influence tumor progression by altering its expression or function." (PMID 40655141, 2025).
tumor (continued). "The methylation status of MZF1 could profoundly impact its function and cancer prognosis, potentially influencing tumor progression through the regulation of gene expression." (PMID 40655141, 2025). "We next hypothesized that the repressing factors SCAND2 and MZF1 were reduced in tumor tissues while HSP90 gene expression was increased in tumor tissues." (PMID 36982267, 2023). "Additionally, the tumor-related fibroblast phenotype can be induced by osteopontin via the regulation of MZF1 and TGF-β." (PMID 37174714, 2023). "MZF1 is a transcription factor of the Krupple family of zinc finger proteins, and MZF1 has been considered to play an important role in the occurrence, invasion and apoptosis of various tumor cells." (PMID 37654657, 2023). "Moreover, TGF-β has been extensively recognized as a carcinogen and a tumor suppressor recently, similar to MZF1." (PMID 37174714, 2023). "Myeloid zinc finger 1 (MZF-1) is a multifaceted transcription factor that may function as either an oncogene or a tumor suppressor, and the molecular bases determining its different traits remain elusive." (PMID 38139336, 2023). "Furthermore, the transcription factor myeloid zinc finger 1 (MZF1) has been shown to mediate tumor cell-induced transformation of mesenchymal stem cells (MSCs) into CAFs." (PMID 38124183, 2023). "SCAND2 and MZF1 RNA were expressed at higher levels in normal tissues than in paired tumor tissues." (PMID 36982267, 2023). "However, MZF1 can also function as a tumor suppressor that, for instance, represses MMP2 in cervical cancer and mediates oncogene-induced senescence." (PMID 36552758, 2022). "MZF1 is reportedly an oncogenic gene that promotes tumor progression." (PMID 36499054, 2022). "In addition, tumor suppressive functions of MZF1-uPEP were mediated, at least in part, through interacting with YY1 protein in NB cells." (PMID 32042322, 2020). "MZF1 can function as a tumor/growth suppressor and controls cell proliferation and tumorigenesis." (PMID 30642258, 2019). "myeloid zinc finger 1 (MZF1) has been observed to be elevated in several cancers, and its excessive expression inhibits apoptosis and promotes the occurrence of tumors, while the silencing of MZF1 leads to reduced tumor growth." (PMID 30961610, 2019). "Although experimental validation is needed, the tumor suppressors/pro-apoptotic factors, MZF1 and the ubiquitous transcription factor STAT1 may be biologically relevant as decreased binding interactions might lower SP140 expression." (PMID 22235315, 2012). "MZF1 can act as a tumor/growth suppressor in the hemopoietic compartment." (PMID 19958507, 2009). "Therefore, panobinostat, by suppressing MZF1 expression, may enhance the tumor-suppressive action of these drugs, thereby improving the overall therapeutic response in cancer treatment." (PMID 40655141, 2025). "Additionally, exploring the role of MZF1 in novel areas such as tumor metabolic reprogramming and therapy resistance could open new frontiers for understanding its functions." (PMID 40655141, 2025). "Through comprehensive bioinformatics enrichment analyses using GSEA and GSVA, it was revealed that MZF1 may regulate various facets of immune responses and immune activation, influencing the delicate balance between tumor immune evasion and anti-tumor immunity." (PMID 40655141, 2025). "However, depending on the context, MZF1 can also function as a tumor suppressor." (PMID 36982267, 2023). "We examined whether SCAND1 and MZF1 could alter tumor cell proliferation and EMT." (PMID 36552758, 2022). "However, the roles of MZF1 in aerobic glycolysis during tumor progression still remain elusive." (PMID 32042322, 2020). "Besides, MZF1 might play key roles also in tumor microenvironment such as mesenchymal stem cell differentiation into cancer-associated fibroblasts." (PMID 31181782, 2019). "In contrast, MZF1 may also act as a tumor suppressor in the tumorigenesis." (PMID 27259238, 2016).